TM4SF1 (transmembrane 4 L six family member 1)
Diseases named in the same sentence as TM4SF1 in open-access papers (continued):
Sharing a sentence is not in itself a finding about the gene and the disease.
cancer (76 papers, 2007 to 2026). A tumor composed of atypical neoplastic, often pleomorphic cells that invade other tissues. "The last decade has seen an increased exploration into the roles of TM4SF1 to further understand its functions in cancer progression and associated molecular mechanisms." (PMID 36678607, 2023). "Using the GEPIA database, we examined the relationship between TM4SF1 and molecules associated with cancer stem cells." (PMID 37069693, 2023). "Numerous studies have shown that TM4SF1 is strongly associated with the occurrence and progression of cancer." (PMID 37069693, 2023). "For instance, the unconventional PDZ-domain-binding motif (X-Tyr-X-Cys) in the C-terminal cytoplasmic portion of TM4SF1 can associate with syntenin-2 and further activates syntenin-1 to participate in cancer cell proliferation and migration." (PMID 35835740, 2022). "As such, in the present report, we explore the associations between the lncRNA BCYRN1, BATF, and TM4SF1 in HCC in an effort to elucidate novel treatment approaches for this deadly cancer." (PMID 35730016, 2022). "Drug resistance is a major cause of treatment failure in cancer patients receiving cytotoxic or targeted therapies for disseminated cancer, and numerous reports have shown that TM4SF1 is positively associated with drug resistance." (PMID 33015133, 2020). "As TM4SF1 expression is higher on the surface of malignant tumors and is significantly associated with cancer development and metastasis, it is an alluring target to antibody-based immunotherapy." (PMID 33015133, 2020). "TM4SF1 is expressed not only in numerous cancers but also in tumor vessels and is associated with angiogenesis." (PMID 33015133, 2020). "Several studies have already confirmed that high TM4SF1 expression in various epithelial malignant tumors can regulate cancer cell invasion and metastasis and is associated with poor prognosis." (PMID 30876464, 2019). "TM4SF1 and SerpinB2 were previously implicated in cancer development particularly in cancer stem cell biology." (PMID 29290987, 2017). "The four genes (HES1, PRKCH, ELF5 and TM4SF1) validated above have all been associated with cancer progression." (PMID 26356672, 2015). "Although the conventional approach is to opt for surface-expressed cancer antigens like the ones mentioned previously, there are efforts to target tumor-associated cells or antigens associated with the vasculature or stroma of the cancer microenvironment, such as TM4SF1 or collagen IV." (PMID 40149295, 2025). "In addition, DDR1 (a subfamily of receptor tyrosine kinases), which functions as a cell surface receptor for cancer cell adhesion, proliferation and differentiation, and migration and invasion, has also been associated with TM4SF1-mediated activities." (PMID 36678607, 2023). "We confirmed via WB, detection of side-population cells, and tumor sphere formation that the overexpression of MYH9 could save the inhibition of cancer stemness in HCC cells caused by the silencing of TM4SF1." (PMID 37069693, 2023). "The reason may be that TM4SF1 is regulated by different signal pathways and different subcellular location of TM4SF1 plays different roles in the development and progression of different malignant tumors, which associated with different clinical prognosis." (PMID 33015133, 2020). "TM4SF1 physically interacts with the membrane and some cytoskeleton-associated proteins to form cell projections named ‘nanopodia’, which are described as frequently identified in multiple types of cancer." (PMID 32000679, 2020). "This localization change of TM4SF1 protein in different tissues might be associated with cancer cell invasion and metastasis." (PMID 30876464, 2019). "Since its discovery, TM4SF1 has received much attention due to its ability to regulate a variety of cellular biological functions in malignant tumors, including motility, proliferation, and apoptosis and its association with the clinical prognosis of cancer patients." (PMID 33015133, 2020).
cancer (continued). "Thus, inhibition of the autophagy of cancer cells may be one of the mechanisms underlying TM4SF1-induced tumorigenesis." (PMID 27153056, 2016). "Previous research has demonstrated that TSPAN proteins, like CD9, CD81, CD151, and TM4SF1, promote cancer metastasis by interacting with integrin α3β1 or α6, which aligns with our functional enrichment results." (PMID 41347075, 2025). "The top five upregulated genes (MMP1, COL10A1, CXCL8, TM4SF1 and PLAU) have been associated with cancer progression and metastasis-inducing mechanisms." (PMID 40640495, 2025). "In vivo models of the human TECs3 phenotype would have utility for preclinical testing of TM4SF1-targeted therapies and for exploring TECs heterogeneity in cancer progression." (PMID 40123905, 2025). "The spatial map of module I aligns well with the cancer regions, as well as the spatial expression of module-associated genes such as KRT17, TM4SF1, and S100A4, which have been reported as PDAC markers." (PMID 40033360, 2025). "The cancer TPCS is an early cancer cell state during tumorigenesis, that is transformed from naturally existing Tm4sf1+ BsP cells by dedifferentiation." (PMID 38582099, 2024). "TM4SF1 positive cancer cell subpopulation (TPCS) was characterized by the upregulation of TM4SF1, ITGA6, and KRT6A." (PMID 38582099, 2024). "Differentially expressed genes (DEGs) between normal urothelium Tm4sf1+ cells (BsP), malignant Tm4sf1+ cells from cancer (TPCS), and normal urothelium Bsc were analyzed." (PMID 38582099, 2024). "In a mouse OHBBN‐induced high‐grade invasive mouse model, Tm4sf1+ cancer cells are the major population that gives rise to further differentiated cancer cells, suggesting that Tm4sf1+ cancer cells serve as the multiple lineage progenitors." (PMID 38582099, 2024). "It is found that a TM4SF1‐positive cancer subpopulation (TPCS) can generate ITH in BLCA, evidenced by integrative single cell atlas analysis." (PMID 38582099, 2024). "In the advanced clinical stage, a progenitor‐like, TM4SF1‐positive cancer cell subpopulation emerges in MIBC driven by BMP signaling and EMT, which contributes to ITH by supporting highly plastic transcriptional phenotypes with its unique epigenome." (PMID 38582099, 2024). "TM4SF1+, SOX4+, and MKI67+ tumor cells; CXCL12+ cancer-associated fibroblasts; CD4+ resident memory T cells; Treg; IgA+ plasma cells; and several myeloid subsets were enriched in stage IV CRC, most of which were associated with overall survival of patients." (PMID 37360193, 2023). "When considering the molecular mechanism by which TM4SF1 affected the cancer stemness in HCC cells, we first considered enriching the pathways of KEGG and GO for TM4SF1 using the GSEA technology." (PMID 37069693, 2023). "The tumor sphere formation test and side-population cell detection also showed that the expression level of TM4SF1 was positively correlated with the cancer stemness of HCC." (PMID 37069693, 2023). "The qPCR and WB detection showed that the expression of TM4SF1, cancer stem–related molecules, the NOTCH pathway–related molecules, and MYH9 in LM3-LR cells was higher than that in the control group." (PMID 37069693, 2023). "Our analysis identified the co-existence of TM4SF1+ cancer cells (clone A) and S1004A+ cancer cells (clone B) with different CD8+ T cells, which is important to understand the interactions between cancer and T cells." (PMID 38040768, 2023). "The result showed an upregulation in the mRNA levels of TM4SF1 in LNCaP cancer cells treated with androgen in the presence of cycloheximide (CHX, a protein synthesis inhibitor)." (PMID 36678607, 2023). "The significant function of TM4SF1 in the incidence and progression of cancer has been widely recognized in recent years." (PMID 37069693, 2023).
cancer (continued). "The relationship between TM4SF1 and cancer stem–related molecules CD44, CD133, OCT4, and SOX2 was detected via qPCR and WB, which confirmed the decrease in the expression of CD44, CD133, OCT4, and SOX2 with the silencing of TM4SF1." (PMID 37069693, 2023). "We found through abundant in vitro and in vivo experiments which the expression of TM4SF1 was positively correlated with the progression and cancer stemness of HCC." (PMID 37069693, 2023). "For instance, TM4SF1 overexpression has been identified in many cancers, including lung, breast, colon, ovarian, prostate, pancreatic, renal, and glioma." (PMID 36678607, 2023). "Further analysis showed that in AIS, except for TM4SF1 + cancer cells, the remaining cancer cells were mainly Clara-like cancer cells, and the biological behavior of such cells was relatively mild." (PMID 36434043, 2022). "Consistent with AIS, central cancer subregion 0 of TD3 was mainly dominated by TM4SF1 + cancer cells (Epi-C0), while peripheral cancer region 2 was mainly dominated by Clara-like cancer cells (Epi-C1)." (PMID 36434043, 2022). "Previous studies have shown that TM4SF1 is overexpressed in various cancers and is strongly upregulated in BC tissues." (PMID 35480865, 2022). "TM4SF1 was proved not only mediating the development of cancer but also the immunotherapeutic sensitivity." (PMID 36568368, 2022). "The hypergeometric distribution showed that in the cancer region, TM4SF1 + cancer cells (Epi-C0) colocalized with the two subtypes of NK cells (T/NK-C4: GNLY and T/NK-C5: NKG7) and mast cells (Mye-C0: TPSB2, Mye-C9: CPA3)." (PMID 36434043, 2022). "We found that Clara-like cancer cells (Epi-C1) were highly enriched in the peripheral region (region 0), and the central region (region 1) was dominated by TM4SF1 + cancer cells (Epi-C0)." (PMID 36434043, 2022). "Regions 0 and 5 of the cancer overlapped with TM4SF1 + cancer cells (Epi-C0), and regions 1 and 3 of the tumor overlapped mainly with CRABP2 + cancer cells (Epi-C3)." (PMID 36434043, 2022). "Despite extremely high tumor heterogeneity, malignant cell markers such as MUC1, CEACAM5, S100A11, CD24, and TM4SF1 were relatively uniformly upregulated in cancer cells and had the potential to serve as targets for SBA diagnosis and treatment." (PMID 36104333, 2022). "As the repopulation of residual tumor cells can lead to cancer recurrence, which depends on the ability of cells to divide, the effect of TM4SF1 on clonogenicity was evaluated using a colony formation assay." (PMID 35153775, 2022). "TM4SF1 has been found to increase the degradation of the extracellular matrix by cancer cells in a variety of tumors, leading to cancer cell invasion and metastasis." (PMID 36568979, 2022). "More important, this group of genes also included genes whose roles in cancer have yet to be fully addressed (e.g., TM4SF1, TM4SF19, EMP1, PHLDA1, and PHLDA2)." (PMID 35831322, 2022). "TM4SF1 represents a potentially viable therapeutic target for the treatment of several cancers owing to its role in the context of tumor growth and progression." (PMID 35730016, 2022). "Previous studies have shown that TM4SF1 is well known for its oncogenic functions in human cancers via the AKT pathway." (PMID 33958586, 2021). "Our study substantiates a novel mechanism by which TM4SF1 maintains cancer cell stemness and EMT via the Wnt/β-catenin/c-Myc/SOX2 axis during the recurrence and metastasis of CRC." (PMID 33153498, 2020). "To investigate the molecular mechanism of TM4SF1 in EMT and cancer stemness, we performed RNA-Seq to identify the differentially expressed genes (DEGs) between TM4SF1-silenced CRC cells and control cells." (PMID 33153498, 2020). "The subcellular expression of TM4SF1 and its expression level regulating by integrins and other tetraspanins can affect the motility of cancer cells." (PMID 33015133, 2020).
cancer (continued). "In nearly all cancers described in this review, increased expression of TM4SF1 promoted the development of cancer and cancer cell migration by inducing EMT, angiogenesis, invadopodia formation, and self-renewal ability." (PMID 33015133, 2020). "The EP1 peptide is a linear B-cell epitope of TM4SF1 that can induce anti-tumor activity against malignant tumor cells that express TM4SF1." (PMID 33015133, 2020). "TM4SF1 promotes the migration and invasion of cancer cells by inducing epithelial-mesenchymal transition, self-renewal ability, tumor angiogenesis, invadopodia formation, and regulating the related signaling pathway." (PMID 33015133, 2020). "Recently, most studies about TM4SF1 have mainly focused on TM4SF1 functions as a direct target of some miRNAs (miR-141, miR-9 miR-206) and its biological function in cancer cells." (PMID 33153498, 2020). "Numerous studies have shown that TM4SF1 plays an indispensable role in promoting cancer cell proliferation and migration through a series of signaling pathways." (PMID 33015133, 2020). "Here, we review the many functions of TM4SF1 in malignant tumors, with the aim to understand the interaction between its expression and the biological behaviors of cancer and to supply a basis for exploring new therapeutic targets." (PMID 33015133, 2020). "Another possibility is that the expression changes of TM4SF1 are only existed in cancer stem-like cells of ESCC." (PMID 27974706, 2017). "Based on these findings, TM4SF1 appears to enhance the invasion of cancer cells by several mechanisms." (PMID 27153056, 2016). "We demonstrated that cell signaling of TM4SF1 mediated chemoresistance in cancer cells by assessing the expression of multidrug resistance (MDR) genes using quantitative RT-PCR." (PMID 26709920, 2015). "Studies have shown that TM4SF1 expression is upregulated in several cancers including HCC." (PMID 40123905, 2025). "TM4SF1, a member of the transmembrane 4 superfamily, is known to facilitate cell motility and adhesion and has been implicated in the promotion of epithelial–mesenchymal transition (EMT), potentially enhancing DDR1’s pro-invasive function in cancer." (PMID 40869052, 2025). "TM4SF1 expression is generally high in cancer cells of epithelial origin, including cancer stem cells, but it is not expressed in cancer cells of hematopoietic origin according to The Cancer Cell Line Encyclopedia as well as our unpublished data." (PMID 41226530, 2025). "TM4SF1 regulates biological and cellular activities through its ability to form 100–300 nm diameter protein complexes called TMEDs (TM4SF1-enriched microdomains) on the surfaces of cells that express high levels of TM4SF1 in vitro and the tumor endothelium of human cancers in vivo." (PMID 39590375, 2024). "In MIBC, a TM4SF1‐positive cancer subpopulation (TPCS) contributed to ITH." (PMID 38582099, 2024). "In particular, TM4SF1 was previously reported as one of the markers of cancer stem cells, suggesting that TM4SF1+ malignant epithelial cells might have the potential to differentiate to other malignant epithelial cell subtypes." (PMID 37360193, 2023). "A study by Tang and colleagues in 2020 showed that TM4SF1 might also have a potential effect on cancer stemness." (PMID 37069693, 2023). "We speculated that TM4SF1 affected not only the cancer stemness of HCC but also the Lenvatinib resistance in HCC because of the close relationship between cancer stemness and tumor drug resistance." (PMID 37069693, 2023). "Compared to other cancer types, one study investigated the biological effects of TM4SF1 on BCa." (PMID 36678607, 2023). "Additionally, TM4SF1 also plays a crucial role in angiogenesis, as its high expression levels have been detected in vascular endothelium cells of human cancers." (PMID 36678607, 2023).
cancer (continued). "Downregulation of TM4SF1 inhibited the migration, invasion, and cancer stemness of CRC cells." (PMID 36816947, 2023). "Studies have confirmed that TM4SF1 is upregulated in a variety of cancers including HCC." (PMID 37069693, 2023). "In order to further confirm whether TM4SF1 is related to the cancer stem of HCC, we isolated CD133+, CD44+ and CD133+/CD44+ cells from LM3 cells with silenced TM4SF1 and LM3 cells from untreated group by flow cytometry." (PMID 37069693, 2023). "We confirmed via tumor sphere formation and side-population cell detection tests that TM4SF1 could affect the cancer stemness in HCC." (PMID 37069693, 2023). "For the cancer cell subtypes, we found that compared with Clara-like cancer cells (Epi-C1) and CRABP2 + cancer cells (Epi-C3), the proportions of both TM4SF1 + (Epi-C0) and UBE2C + (Epi-C6) cancer cells were constantly increased during the invasive process of LUAD and dramatically elevated in IAC." (PMID 36434043, 2022). "We found that TM4SF1 expression was positively correlated with the upregulation of genes during epithelial–mesenchymal transition —a key event in epithelium-derived cancer cell migration and dissemination to metastatic organs." (PMID 36568979, 2022). "Although accumulating evidence suggests that overexpressed TM4SF1 can contribute to the development, progression, and drug resistance of many malignant tumors, the biological functions and involved mechanisms of TM4SF1 in ESCC remain largely unknown." (PMID 35835740, 2022). "It is worthy of note that the role of TM4SF1 in cancer remains controversial." (PMID 35835740, 2022). "However, in TNBC cell lines 4T1 and MDA-MB-231 cells, TM4SF1 promotes cancer stem cell traits mechanistically by coupling DDR1 to PKCα and augmenting JAK-STAT signaling." (PMID 35153775, 2022). "In summary, combined detection of CCL18 and CXCL1 chemokines, and C1D, TM4SF1, FXR1, and ZNF573 autoantibodies can improve the specificity and sensitivity of OC diagnosis, and its diagnostic efficiency is higher than that of other malignant tumors." (PMID 34995016, 2022). "TM4SF1 is a highly expressed cell surface antigen which mediates signal transduction events that facilitate cell development, growth, invasion, and metastasis in different carcinomas." (PMID 35641855, 2022). "These promising findings in other cancers, together with our findings in the present study, lead us to suggest that the potential role of TM4SF1 and IGFBP3 as predictive biomarkers of response to vinflunine treatment in aUCC merits further study in a larger cohort of patients." (PMID 34944855, 2021). "Therefore, a hypoxia-responsive lncRNA-SNHG12/miR-194-3p/TM4SF1 or HIF-1A ceRNA network is likely to present in the cancer tissues of HCC patients, and the ceRNA network is involved in tumor development and is related to patient prognosis." (PMID 33690171, 2021). "The present study established a link between Kras active mutation and beta‐catenin/TCF signalling, and indicated that targeting the TM4SF1‐mediated activation of the beta‐catenin/TCF cascade might be helpful for the therapy of KrasG12D‐driven cancer." (PMID 31876386, 2021). "TM4SF1 is an independent prognostic indicator and biomarker in several cancers." (PMID 33015133, 2020). "Induction of T-cell immune reactions against TM4SF1 may be a meaningful therapeutic approach for diverse cancers." (PMID 33015133, 2020). "This interaction might be critical for the biological function of TM4SF1 because syntenin-1 is involved in cancer cell proliferation and migration." (PMID 33015133, 2020). "The close relationship between TM4SF1 and clinical prognosis makes it a valid biomarker for cancer diagnosis, and as TM4SF1 may promote drug resistance in cancer, it is also a potential therapeutic target." (PMID 33015133, 2020). "Due to the clustering of TM4SF1 on the cell surface, this antibody could kill TM4SF1-positive cancer cells and inhibit cancer cell invasion." (PMID 33015133, 2020).